RNU6-876P (RNA, U6 small nuclear 876, pseudogene)
Gene: Small nuclear RNA gene on chromosome 11 (128,993,237 to 128,993,340, reverse strand). Ensembl gene ENSG00000212597.
Homologues: Orthologues: chimpanzee U6 (100% identical), macaque U6 (97% identical), dog U6 (77% identical). Paralogues in human: RNU6-1175P (86% identical), RNU6-11P (86% identical), RNU6-23P (86% identical), RNU6-312P (86% identical), RNU6-37P (86% identical), RNU6-774P (86% identical), RNU6-1088P (85% identical), RNU6-1209P (85% identical), RNU6-1332P (85% identical), RNU6-38P (85% identical), RNU6-480P (85% identical), RNU6-560P (85% identical), and 1284 more.